RN7SL722P (RNA, 7SL, cytoplasmic 722, pseudogene)
Gene: Miscellaneous RNA gene on chromosome 9 (61,789,143 to 61,789,426, forward strand). Ensembl gene ENSG00000273940.
Homologues: Orthologues: chimpanzee Metazoa_SRP (99% identical), macaque Metazoa_SRP (94% identical). Paralogues in human: RN7SL565P (100% identical), RN7SL787P (99% identical), RN7SL52P (99% identical), RN7SL544P (99% identical), RN7SL763P (99% identical), RN7SL205P (97% identical), RN7SL1 (81% identical), RN7SL2 (81% identical), RN7SL3 (81% identical), RN7SL322P (80% identical), RN7SL230P (80% identical), RN7SL709P (80% identical), and 704 more.